MRI1 (methylthioribose-1-phosphate isomerase 1)
Description:
Catalyzes the interconversion of methylthioribose-1-phosphate (MTR-1-P) into methylthioribulose-1-phosphate (MTRu-1-P). Independently from catalytic activity, promotes cell invasion in response to constitutive RhoA activation by promoting FAK tyrosine phosphorylation and stress fiber turnover.
Synonyms: M1Pi; MRDI; MGC3207; Ypr118w; mtnA
Tractability: PROTAC: ubiquitination databases record sites on it; its protein half-life has been measured.
Gene: Protein-coding gene on chromosome 19 (13,764,522 to 13,774,282, forward strand). Ensembl gene ENSG00000037757.
Subcellular location: Nucleus; Cytoplasm; Cell projection
Subcellular location (Human Protein Atlas): Cytosol; Nucleoplasm; Nucleoli fibrillar center
Pathways (Reactome):
Metabolism: Methionine salvage pathway
Gene Ontology:
Molecular function: identical protein binding; protein binding; S-methyl-5-thioribose-1-phosphate isomerase activity
Biological process: S-adenosylmethionine cycle; L-methionine salvage
Cellular component: nucleoplasm; cytosol; cytoplasm; nucleus
Genetic constraint (gnomAD): Loss-of-function variants: 27 observed, 23.94 expected, observed/expected ratio (o/e) 1.13, 90% interval 0.83 to 1.55. The upper end of that interval is the gene's LOEUF score, 1.55, which puts it in group 6 of 6, group 1 being the genes least tolerant of losing a copy. Missense variants: 496 observed, 458 expected, observed/expected ratio (o/e) 1.08, 90% interval 1 to 1.17. Synonymous variants: 211 observed, 206.89 expected, observed/expected ratio (o/e) 1.02, 90% interval 0.91 to 1.14.
Homologues: Orthologues: chimpanzee MRI1 (99% identical), pig MRI1 (90% identical), dog MRI1 (89% identical), macaque MRI1 (89% identical), mouse Mri1 (86% identical), guinea pig MRI1 (85% identical), rabbit MRI1 (85% identical), rat Mri1 (77% identical), tropical clawed frog mri1 (66% identical), zebrafish mri1 (66% identical), Drosophila melanogaster CG11334 (59% identical), Caenorhabditis elegans C01G10.9 (40% identical). Paralogues in human: EIF2B4 (24% identical), EIF2B1 (18% identical), EIF2B2 (18% identical).
Diseases named in the same sentence as MRI1 in open-access papers:
MRI1 is named in the same sentence as 4 diseases in open-access papers, as found by Europe PMC text mining. Sharing a sentence is not in itself a finding about the gene and the disease. The quoted sentences say what the papers report.
ovarian carcinoma (1 paper, 2022). A malignant neoplasm originating from the surface ovarian epithelium. "As MRI1 is related to promoting glutathione signaling, and for GSS, the specific role of MRI1 in decreasing the risk of disease progression in ovarian cancer will require further investigation to understand whether this protein promotes tumor cell survival through mitigating oxidative stress." (PMID 36195845, 2022).
cancer (1 paper, 2024). A tumor composed of atypical neoplastic, often pleomorphic cells that invade other tissues. "These specific metabolic flux–related genes, such as DNM2 (endocytosis), APOC1 (lipid transport), MRI1 (L-methionine salvage), MTAP (NAD salvage), and SLC29A1 (nucleoside import), indicate that the cancer progenitor cells represent hubs of metabolic trafficking activities." (PMID 38649187, 2024).
MRI1 also shares sentences with these, for which no sentence is quoted: infection (1 paper); tumor (1).